ACE (angiotensin I converting enzyme)
Diseases named in the same sentence as ACE in open-access papers (continued):
Sharing a sentence is not in itself a finding about the gene and the disease.
Hypertension (continued). "Moreover, ACE was found in human urine and associated with hypertension." (PMID 23646149, 2013). "Thus, the objective of the present study was to analyze whether these polymorphisms or given haplotypes are associated with essential hypertension and ACE serum levels in Mexican Mestizo individuals." (PMID 23741507, 2013). "Therefore, the aim of this study was to investigate the presence of the urinary 90 kDa N-domain ACE in a large cohort of the general population and to determine its association with presence of hypertension and with associated factors that can contribute to development of high blood pressure." (PMID 22666552, 2012). "The aim of this paper was to investigate the presence of the urinary 90 kDa N-domain ACE in a cohort of the population from Vitoria, Brazil, to verify its association with essential hypertension since this isoform could be a possible genetic marker of hypertension." (PMID 22666552, 2012). "Pharmacological treatment of hypertension consists in the use of drug therapies including association or not of diuretics, beta-blockers, calcium channel blockers, angiotensin converting enzyme (ACE) inhibitors and angiotensin II receptor (AT1) antagonist (ARA)." (PMID 21623317, 2011). "In addition, we sought to determine if the BP response following acute endurance exercise was altered by interactions among dietary calcium intake and two RAS polymorphisms associated with hypertension, i.e., ACE I/D and AT1R A/C, that we and others have shown alter postexercise hypotension." (PMID 17204161, 2007). "Several ACE inhibitors, which bind to both cACE and nACE active sites, are used clinically for the treatment of hypertension; however, serious side effects are seen in ~ 20–25% of patients due to nonselective inhibition." (PMID 40824896, 2026). "Certain CT features appeared more common in patients requiring therapeutic exploration, while hypertension and ACE inhibitor use were observed more frequently among patients with negative exploration." (PMID 41728481, 2026). "This study highlights deep-sea mollusks as an important source of novel ACE inhibitory peptides, contributing to the development of new therapeutic ingredients or functional food agents against hypertension." (PMID 41828750, 2026). "Hypertension and angiotensin-converting enzyme (ACE) inhibitor use were more commonly observed among patients with negative exploration." (PMID 41728481, 2026). "Inhibition of ACE is therefore an effective strategy for the treatment of hypertension, and there are currently 17 ACE inhibitors in clinical use." (PMID 40824896, 2026). "This review explores these dual challenges by examining the pharmacogenetic landscape of hypertension, with a focus on three clinically relevant genes: ACE, AGTR1, and CYP2C9." (PMID 41723221, 2026). "Hypertension is a globally prevalent chronic cardiovascular disease, with angiotensin-converting enzyme (ACE) serving as a key target for therapeutic intervention." (PMID 41750855, 2026). "Background and Clinical Significance: Angiotensin-converting enzyme inhibitors (ACE-Is) are commonly used for treatment of hypertension and are well known among primary care specialists." (PMID 42029474, 2026). "Do you (or did you so in the last 6 months) take an ACE inhibitor?(ACE-inhibitors are drugs to treat heart or kidney diseases (e.g. high blood pressure) and their active substances are named with the ending -pril, e.g. captopril, ramipril, or enalapril)." (PMID 41601695, 2026). "In this particular situation, the most favored pharmacological agents for managing hypertension are ACE inhibitors and dihydropyridine calcium channel blockers." (PMID 41466807, 2025). "This pattern suggests either more frequent indications for ACE inhibitors or ARB use among younger patients or a more severe course of hypertension in the younger group." (PMID 41464543, 2025). "A total of 94.2% of the subjects had hypertension, with most receiving ACE inhibitor therapy (63.8%)." (PMID 39852146, 2025).
Hypertension (continued). "Guidelines recommend thiazide diuretics, angiotensin‐converting enzyme (ACE) inhibitors, angiotensin receptor blockers (ARBs), and calcium channel blockers (CCBs) as first-line primary agents for hypertension treatment." (PMID 40468725, 2025). "First-line therapies for hypertension and heart failure include antihypertensive agents, such as Angiotensin-Converting Enzyme inhibitors (ACE) inhibitors and Angiotensin Receptor Blockers (ARBs), which reduce cardiovascular events." (PMID 41406476, 2025). "It is likely that HLO rectified the cardiovascular hypertrophy in hypertension by inhibiting ACE and reducing AT1 receptor/gp91phox." (PMID 40076524, 2025). "For example, both ACE inhibitors and angiotensin receptor blockers have been shown to regress interstitial fibrosis in patients with hypertension and increased collagen volume fraction." (PMID 40597238, 2025). "The commercial chemosynthetic ACE inhibitors, including captopril, enalapril, and benazepril, exhibit significant therapeutic efficacy for hypertension." (PMID 41471840, 2025). "Angiotensin I-converting enzyme (ACE) plays a pivotal role in regulating human blood pressure, and serves as an ideal target for the treatment of hypertension." (PMID 40807557, 2025). "Captopril, a widely used angiotensin-converting enzyme (ACE) inhibitor for the treatment of hypertension, was employed as a positive control in this study." (PMID 40872547, 2025). "The decline in AAMRs is consistent with improvements in hypertension control, pharmacologic interventions (e.g., ACE inhibitors, beta-blockers), and increased awareness of cardiovascular risk factors." (PMID 40565965, 2025). "One of the most successful examples is captopril, the first angiotensin-converting enzyme (ACE) inhibitor approved for the treatment of hypertension and heart failure." (PMID 40864047, 2025). "In Japan, as with calcium channel blockers, angiotensin II receptor blockers, diuretics, and beta-blockers, ACE inhibitors are considered the first-line treatment for hypertension." (PMID 41073682, 2025). "Various types of mushrooms have the potential to reduce hypertension by suppressing the activity of the hypertension Angiotensin-converting enzyme (ACE)." (PMID 40837429, 2025). "Both hypertension and diabetes, particularly when treated with ACE inhibitors or angiotensin II receptor blockers (ARBs), are associated with elevated ACE2 expression, potentially facilitating enhanced viral entry and replication." (PMID 39891219, 2025). "The administration of fucoxanthin, which was extracted from the brown seaweed Sargassum wightii, significantly reduced blood pressure and the activity of the angiotensin-I-converting enzyme in diabetic rats with hypertension." (PMID 40143179, 2025). "ACE inhibition is a well-established therapeutic strategy for the management of hypertension, as ACE catalyzes the formation of angiotensin II, a potent vasoconstrictor." (PMID 41515425, 2025). "Inhibition of angiotensin‐converting enzyme (ACE) activity has emerged as a primary therapeutic strategy for the management of hypertension." (PMID 40255548, 2025). "RASIs, such as direct renin inhibitors, angiotensin II receptor blockers (ARBs), and angiotensin-converting enzyme inhibitors (ACE-Is) are frequently used to manage hypertension and heart failure." (PMID 41417371, 2025). "A statistically significant increase in the proportion and level of xerostomia was observed in the hypertension group in research that gathered data on patients treated with ACE inhibitors, calcium channel blockers, β-adrenergic blockers, and diuretics." (PMID 41294894, 2025). "Earlier studies on hypertension have focused on this subsequent cleavage of angiotensin-1 by the angiotensin-converting enzyme ACE, with the role of angiotensinogen being initially relegated to that of a passive substrate." (PMID 40699774, 2025).
Hypertension (continued). "In line with this, the American Diabetes Association recommends maximizing the dose of either an ACE inhibitor or an ARB in patients with diabetes, hypertension, and albuminuria to prevent CKD progression." (PMID 40660221, 2025). "HN also benefits from ACE inhibitors (African American Study of Kidney Disease and Hypertension (AASK) trial), especially in proteinuric cases, though other antihypertensives are suitable for non-proteinuric HN." (PMID 41141162, 2025). "Pharmacologic RAAS blockade with angiotensin-converting enzyme (ACE) inhibitors or angiotensin receptor blockers (ARBs) is widely used in clinical cardiology to treat hypertension and heart failure." (PMID 40943088, 2025). "Prior studies have shown that peptides with high hydrophobicity can effectively prevent oxidation and hypertension by binding to Keap1 and ACE, respectively." (PMID 40077777, 2025). "Lipid-lowering agents were the most used (n = 9), followed by antidepressants (n = 8), and ACE inhibitors or angiotensin receptor blockers (n = 7) for hypertension." (PMID 40952626, 2025). "Enalapril is an angiotensin-converting enzyme (ACE) inhibitor (ACEi) which is widely used in the management of (paediatric) hypertension and heart failure (HF)." (PMID 40356784, 2025). "In the present study, we found higher rates among men using calcium channel blockers and ACE inhibitors, but a lower rate of ARBs; and higher rates among men with hypertension and concomitant CHD using ASA (aspirin)." (PMID 39863859, 2025). "Use ACE inhibitors (ACEIs) or angiotensin receptor blockers (ARBs) as the first-line antihypertensive treatment in T2D patients with hypertension." (PMID 40741551, 2025). "ACE inhibitors are used to treat hypertension and prevent renal impairment, along with other ailments, in patients with lupus." (PMID 41458657, 2025). "Several types of antihypertensive agents are available for the treatment of hypertension in adults, including angiotensin-converting enzyme (ACE) inhibitors, angiotensin II receptor blockers, calcium channel blockers, and diuretics." (PMID 40732315, 2025). "As one of the key therapeutic targets for hypertension management, angiotensin-I-converting enzyme (ACE, EC 3.4.15.1) plays a pivotal role in blood pressure regulation through the renin-angiotensin system." (PMID 41517150, 2025). "Second, the dietary fiber intake improves hypertension by its effect on arterial contraction, influencing the angiotensin-converting enzyme (ACE) activity and retaining electrolytes (such as potassium and magnesium) in its matrix." (PMID 40566549, 2025). "These comprehensive findings emphasize the promising therapeutic potential of 2 as an ACE inhibitor, paving the way for further exploration of Senecio nutans compounds in the context of hypertension treatment and vascular function modulation." (PMID 40332402, 2025). "Around 1.4 billion people worldwide suffer from hypertension, with thiazide diuretics, ACE inhibitors, and calcium channel blockers being the most commonly recommended first-line treatments." (PMID 40004206, 2025). "Among OFG patients with hypertension, 2 out of 3 were under ACE-inhibitors and one patient was under the combination ACE inhibitor/thiazide diuretic." (PMID 40396174, 2025). "A total of 6319 (27%) patients had a history of comorbidities typically managed with BBs, ACE inhibitors/ARBs, or CCBs—including 5628 (24%) patients who had a history of hypertension." (PMID 41163361, 2025). "Participants also reported starting additional medications to manage comorbid conditions, such as ACE inhibitors for hypertension or anticoagulants to prevent future strokes." (PMID 40686568, 2025). "ACE inhibitors are widely used to treat hypertension, and ACE is an important target for hypertension treatment." (PMID 40370871, 2025).
Hypertension (continued). "In one patient with left internal carotid artery occlusion (LICO), a decrease in BP from 140/79 mm Hg to 128/78 mm Hg was observed after enalapril administration, reflecting the efficacy of ACE inhibitors for hypertension management." (PMID 41323461, 2025). "Patients with hypertension, heart failure, or those taking angiotensin-converting enzyme (ACE) inhibitors or angiotensin II receptor blockers are at higher risk." (PMID 41283270, 2025). "ACE inhibitors are widely prescribed for the treatment of hypertension and various cardiovascular conditions and are considered among the most effective classes of antihypertensive agents." (PMID 40710492, 2025). "The current guidelines recommend initiating pharmacological treatment in hypertension patients, typically with low-dose ACE inhibitors/ARBs and/or dihydropyridine/CCBs as a first step, then full dose as a second step, and finally, adding diuretics." (PMID 39912900, 2025). "applied the active peptide KYPHVF (KF6) to control hypertension by inhibiting ACE activity and reported that KF6 reduced the abundance of Alistipes to regulate the composition of the gut microbiota." (PMID 40104285, 2025). "Inhibiting Angiotensin I-converting enzyme (ACE) is one of the effective strategies for treating hypertension due to its core functions in the renin-angiotensin system (RAS) and the kallikrein-kinin system (KKS)." (PMID 41471840, 2025). "The majority of patients presented hypertension (58.3%), and 33.3% were on treatment with ACE inhibitors." (PMID 39928271, 2025). "Angiotensin converting enzyme (ACE) inhibitors are one of the most frequently used class of antihypertensive drugs in patients with hypertension, including those with RHTN." (PMID 40534840, 2025). "Angiotensin I-converting enzyme inhibitory (ACEI) peptides have attracted increased research attention owing to their ability to effectively inhibit ACE activity and their significant effects on the prevention and treatment of hypertension." (PMID 40807557, 2025). "In this context, angiotensin-converting enzyme (ACE) inhibitors (ACEIs), such as lisinopril and captopril, and putative biopeptides are medications used to manage hypertension, heart failure, and kidney diseases like diabetic nephropathy." (PMID 40809316, 2025). "Additional comorbidities included well-controlled arterial hypertension managed with an angiotensin-converting enzyme (ACE) inhibitor and hypercholesterolemia treated with a statin." (PMID 41190083, 2025). "Several forms of pharmacotherapy commonly used to treat hypertension are thiazide diuretics, angiotensin-converting enzyme (ACE) inhibitors, α- and β-blockers, and α-adrenoceptor agonists." (PMID 40814063, 2025). "TRF effectively reduced systolic BP, mean BP, diastolic BP, and BW; improved hypertension-induced cardiac structural and functional damage; and inhibited the ACE-Ang-II-AT1 axis in circulating and LV tissues." (PMID 40179126, 2025). "Although other subgroups, such as patients with hypertension, those on ACE inhibitors/ARBs or beta-blockers, or those with low nutritional vitamin D, showed non-significant trends (p > 0.05), the OR was generally higher in the VDD group." (PMID 40362848, 2025). "Enalaprilat is an IV ACE inhibitor recommended for paediatric patients with high renin hypertension, renovascular hypertension, or reno-parenchymal hypertension." (PMID 41007039, 2025). "In our study, we discovered that enalapril, a commonly prescribed ACE inhibitor for hypertension, has significant anti-senescence effects at both the cellular and organismal levels." (PMID 40874922, 2025). "AngII receptors and ACE are pharmacologically inhibited in the treatment of patients with hypertension and HF." (PMID 40699836, 2025).
Hypertension (continued). "In this model, changes in LVEF and WMSI emerged as the most relevant factors for MACE prediction, along with symptom-to-balloon time, body mass index, diabetes mellitus, hypertension, prior revascularization, beta-blocker therapy, and ACE inhibitor therapy." (PMID 40438233, 2025). "We mainly delivered a tailored therapy for a reduced LVEF or hypertension (ACE inhibitors) and symptom relief (like β-blockers for palpitations, or ACE inhibitors/diuretics for dyspnea)." (PMID 40870490, 2025). "In individuals with CKD, the administration of ACE inhibitors or angiotensin receptor blockers is warranted to control hypertension, diminish proteinuria, and impede the advancement of kidney disease." (PMID 39996706, 2025). "High blood pressure (hypertension) is usually regulated by angiotensin-converting enzyme (ACE) via the kinin-kallikrein system (KKS) and the renin-angiotensin-aldosterone system (RAAS)." (PMID 41209547, 2025). "Managing hypertension and diabetes is key to preserving kidney function, with monitoring of serum CR and potassium after starting ACE inhibitors/ARBs, MRAs, or diuretics to control cardiovascular risks." (PMID 40143742, 2025). "Our expert panel opinion, therefore, emphasizes screening at every visit and the use of renin–angiotensin system blockers (ACE inhibitors or ARBs) as first-line agents when hypertension coexists with diabetes." (PMID 41299307, 2025). "ACE inhibitors and angiotensin receptor blockers (ARBs) are recommended as the first-line medications for the treatment of hypertension." (PMID 40116328, 2025). "ACE inhibitors or ARBs are first-line in diabetes with hypertension and albuminuria because they lower intraglomerular pressure and reduce albuminuria." (PMID 41299307, 2025). "This potency, stability, and distinct mechanism support the potential of ACE-inhibitory tripeptides for functional foods or complementary hypertension therapies." (PMID 41209547, 2025). "Betaine has been demonstrated to reduce hypertension by inhibiting ACE activity, with ACE inhibition ranging from 4.72% to 86.97% in undigested solid samples." (PMID 40255548, 2025). "The genetic variants of ACE and AGTR1 can be justifiably considered candidate genes related to the pathogenesis of hypertension in diabetes." (PMID 40149592, 2025). "Dysphagia was documented in 38.10% of the stage 4 group, and over half (55.56%) of the stage 4 group had hypertension, and other disorders of fluid, electrolyte and acid–base balance (52.38%), with (60.32%) prescribed ACE-inhibitors." (PMID 40804403, 2025). "In the management of hypertension, angiotensin‐converting enzyme (ACE) inhibitors are frequently prescribed." (PMID 41049420, 2025). "The use of ACE inhibitors or ARBs was assessed only in patients with hypertension or relevant indications for these medications, and adherence to these therapies increased from 36.8% to 73.6% (p < 0.001)." (PMID 40457605, 2025). "The data on the inhibition of ACE and AChE activity and advanced glycation end-products (AGEs) formation are important against hypertension, Alzheimer-type dementia, and diabetic complications, respectively." (PMID 41155415, 2025). "Beta-blockers and ACE inhibitors are essential in managing hypertension, heart failure, and other cardiovascular conditions, significantly reducing morbidity and mortality." (PMID 40400633, 2025). "Both synthetic antihypertensive agents, such as ACE inhibitors (e.g., captopril), and food-derived bioactive peptides have demonstrated that targeting ACE is an effective strategy for hypertension management." (PMID 40649326, 2025). "This inhibition nicely paralleled the effect of Captopril, a synthetic analog of the ACE-inhibiting peptide found in the Jararaca snake venom and a drug of reference that is widely used to treat hypertension." (PMID 40284196, 2025).